TMEM263 (transmembrane protein 263)
Description:
May play a role in bone development.
Synonyms: C12orf23; MGC17943
Tractability: Antibody: UniProt predicts a signal peptide or a membrane-spanning region. PROTAC: ubiquitination databases record sites on it; its protein half-life has been measured.
Gene: Protein-coding gene on chromosome 12 (106,955,667 to 106,978,778, forward strand). Ensembl gene ENSG00000151135.
Subcellular location: Membrane
Subcellular location (Human Protein Atlas): Vesicles
Gene Ontology:
Cellular component: membrane
Genetic constraint (gnomAD): Loss-of-function variants: 1 observed, 5.09 expected, observed/expected ratio (o/e) 0.2, 90% interval 0.069 to 0.93. That is too few expected variants to judge how well the gene tolerates losing a copy. Missense variants: 91 observed, 122.98 expected, observed/expected ratio (o/e) 0.74, 90% interval 0.62 to 0.88. Synonymous variants: 43 observed, 42.39 expected, observed/expected ratio (o/e) 1.01, 90% interval 0.79 to 1.31.
Homologues: Orthologues: chimpanzee TMEM263 (100% identical), macaque TMEM263 (100% identical), pig TMEM263 (98% identical), dog TMEM263 (97% identical), mouse Tmem263 (97% identical), rabbit TMEM263 (97% identical), rat Tmem263 (97% identical), guinea pig TMEM263 (93% identical), tropical clawed frog tmem263 (76% identical), zebrafish tmem263 (75% identical).
Diseases named in the same sentence as TMEM263 in open-access papers:
TMEM263 is named in the same sentence as 13 diseases in open-access papers, as found by Europe PMC text mining. Sharing a sentence is not in itself a finding about the gene and the disease. The quoted sentences say what the papers report.
dwarfism (3 papers, 2021 to 2024). "Single nucleotide polymorphisms in TMEM263 are associated with bone mineral density in humans and mutations are associated with dwarfism in chicken and severe skeletal dysplasia in at least one human fetus." (PMID 38241182, 2024). "Intriguingly, a nonsense mutation (Trp59*) that truncates the TMEM263 protein is linked to dwarfism in chicken, although it is unclear if this mutation directly causes dwarfism." (PMID 38241182, 2024). "Since mutation in TMEM263 is linked to human skeletal dysplasia and dwarfism in chicken, and TMEM263 is also a GWAS candidate gene for BMD, we speculated that TMEM263 may be a novel regulator of the GH/IGF-1 axis." (PMID 38241182, 2024). "Lastly, Tmem263-KO male mouse liver DEGs were compared to those of Stat5b-KO male mice, which exhibit dwarfism and GH pulse resistance." (PMID 38241182, 2024). "Since TMEM263 has not yet been associated with postnatal dwarfism in human, it should be considered a potential candidate gene in screening children with idiopathic growth failure." (PMID 38241182, 2024).
autism (1 paper, 2025). Persistent deficits in social interaction and communication and interaction as well as a markedly restricted repertoire of activity and interest as well as repetitive patterns of behavior. "Several of these functionally uncharacterized proteins are associated with human diseases including ciliary dyskinesia (CLXN), Lui-Jee-Baron syndrome (SPIN4), lymphoblastic leukemia (LNP1, SLX4IP), lethal skeletal dysplasia (TMEM263), and association to autism and fragile X syndrome (DIPK2B)." (PMID 40425816, 2025).
COVID-19 (1 paper, 2022). A disease caused by infection with severe acute respiratory syndrome coronavirus 2. "Among them, six (ADK, DHFR, METAP2, PIN4, SC5D, and TMEM263) had matching risk factor genes showing consistent patterns, i.e., transcriptional downregulations increased the COVID-19 mortality risk." (PMID 35547187, 2022).
epilepsy syndrome (1 paper, 2021). A syndrome that has a characteristic cluster of clinical features and/or lectroencephalographic (EEG) findings that reflect underlying epileptic activity. "Because dysfunction of the Slick gene leads to infantile epileptic encephalopathy type 57, TMEM263 gene dysfunction may also be involved in genetic disorders of the nervous system and epilepsy syndromes." (PMID 34238371, 2021).
Laron-type dwarfism (1 paper, 2024). "Nevertheless, it is tempting to speculate on the possibility that rare homozygous loss-of-function mutations and variants of TMEM263 may cause Laron-type dwarfism with characteristic GHI." (PMID 38241182, 2024).
skeletal dysplasia (2 papers, 2021 to 2024). Any Mendelian diseases that affects growth and development of the skeleton. "To date, there is only one documented case of a loss-of-function mutation in TMEM263, and it was associated with severe skeletal dysplasia in a fetus." (PMID 38241182, 2024). "In this study, using WES, we have identified TMEM263 mutation as a new severe lethal skeletal dysplasia causative mutation." (PMID 34238371, 2021). "Whole exome sequencing (WES) identified a homozygous frameshift mutation in the TMEM263 gene in a fetus with severe lethal skeletal dysplasia." (PMID 34238371, 2021). "Altogether, these transcriptomic data provide supporting evidence that the underlying cause of the severe growth retardation and skeletal dysplasia seen in Tmem263-KO mice is most likely attributed to disrupted GH signaling in the liver and possibly other organs such as the bone." (PMID 38241182, 2024). "Together, these data point to reduced hepatic GHR expression and GHI as potentially contributing to growth failure and skeletal dysplasia seen in the Tmem263-KO animals." (PMID 38241182, 2024). "The growth retardation and skeletal dysplasia phenotypes seen in Tmem263-KO mice strongly suggest a potential deficit in the GH/IGF-1 axis." (PMID 38241182, 2024). "Together, these data indicate that low IGF-1, IGFBP3, and IGFALS levels likely contribute to growth retardation and skeletal dysplasia in Tmem263-KO mice." (PMID 38241182, 2024). "TMEM263 can be considered as a new gene responsible for skeletal dysplasia." (PMID 34238371, 2021). "Consequently, Tmem263 knockout (KO) mice had low circulating IGF-1 and IGF binding protein 3 (IGFBP3), leading to dramatic postnatal growth failure and skeletal dysplasia." (PMID 38241182, 2024).
TMEM263 also shares sentences with these, for which no sentence is quoted: ciliary dyskinesia (1 paper); fragile X syndrome (1); growth failure (1); Lethal skeletal dysplasia (1); Lui-Jee-Baron syndrome (1); lymphoblastic leukemia (1); Sepsis (1).